IL2 (interleukin 2)
Diseases named in the same sentence as IL2 in open-access papers (continued):
Sharing a sentence is not in itself a finding about the gene and the disease.
cervical dystonia (1 paper, 2024). "The same study also showed an increased population of B cells, monocytes, and an increased ratio of CD8+ cytotoxic cells compared to CD4+ helper cells with an increase in proinflammatory cytokines like IL-5, IL-2, PIGF, VEGF-D, IL-1ß in patients of cervical dystonia." (PMID 39651491, 2024).
chondrosarcoma (1 paper, 2005). A malignant cartilaginous matrix-producing mesenchymal neoplasm arising from the bone and soft tissue. "TIL were able to isolate successfully from small tumor fragments (wet weight < 5 g) immediately after the biopsy except for chondrosarcoma, fibrous dysplasia and 50% of bone metastases and maintained for 3 weeks in the presence of 300 UI/ml IL-2 for flow cytometric analyses." (PMID 16188028, 2005).
Chronic fatigue (1 paper, 2023). Subjective feeling of tiredness characterized by a lack of energy and motivation that persists for six months or longer. "In vivo, JP could increase the levels of IL-2, IL-4, and IL-10 in the serum of mice treated with cyclophosphamide, increase the level of IL-2 in the serum of chronic fatigue (CFS) rats, and decrease the level of IL-10." (PMID 37959774, 2023).
chronic thromboembolic pulmonary hypertension (1 paper, 2024). Chronic thromboembolic pulmonary hypertension (CTEPH) is characterized by the persistence of thromboemboli in the form of organized tissue obstructing the pulmonary arteries. "Also, in patients with chronic thromboembolic pulmonary hypertension (CTEPH), different cytokines showed increased levels, such as IL-1β, IL-2, IL-4, IL-6, IL-8 and IL-10." (PMID 38612795, 2024).
chronic viral hepatitis (1 paper, 2013). "Currently, only INF-alpha is used in the treatment of chronic viral hepatitis because the effectiveness of the exogenous administration of IL12, IL2 and IL10 is unclear." (PMID 24130726, 2013).
cleft lip (1 paper, 2021). Congenital defect in the upper lip where the maxillary prominence fails to merge with the merged medial nasal prominences. "The consistent expression of IL-2,6,13 and TNF-α in the cleft lip and palate affected tissue indicates the role of these cytokines in the pathogenesis of these anomalies." (PMID 33673258, 2021).
colon adenoma (1 paper, 2024). An adenoma that arises from the colon. "IFN-γ, TNF-α, and IL-2 enhance cytotoxic and apoptotic effects in response to colon adenomas." (PMID 38343544, 2024).
colon disorder (1 paper, 2025). "IBD is a colon disorder associated with increased levels of proinflammatory cytokines, including tumor necrosis factor-a, interleukin (IL)-1b, IL-2, and IL-6." (PMID 39979878, 2025).
denture stomatitis (1 paper, 2022). Inflammation of the mouth due to denture irritation. "The results also show that the salivary concentration of cytokine IL-2 was reduced, and this outcome can be justified by the association between Candida albicans and elevated interleukin-2 production in cultures from patients with and without denture stomatitis." (PMID 36289978, 2022).
dermatomycosis (1 paper, 2019). Superficial infections of the skin or its appendages by any of various fungi. "The levels of IL-2 reached the highest on the last day of measurement, indicating that the T cell activity correlated with the severity of dermatomycosis." (PMID 31579583, 2019).
dermatophytosis (1 paper, 2023). A common fungal infection of the stratum corneum of the skin, hair, or nails by a dermatophyte. "Our biosynthesized AS-AgNPs recapitulate the effect of nitric oxide-releasing AgNPs, which have been recently shown to down-regulate the production of IL-2, 6, 10 and TNFα, upon topical application in a mouse model of T. rubrum dermatophytosis." (PMID 36838531, 2023).
dilatation (1 paper, 2022). "IL-2 therapy was associated with significant LV dilatation, a strong trend towards a reduction in LV EF and significantly increased LV mass in comparison to healthy volunteers." (PMID 35741162, 2022). "High dose IL-2 was associated with acute cardiopulmonary capillary leak, myocardial and pulmonary tissue oedema and cardiomyocyte injury, which resulted in an acute increase in LV mass, LV dilatation, reduced LV function and QT prolongation." (PMID 35741162, 2022). "High dose IL-2 therapy is ubiquitously associated with acute cardiopulmonary inflammation, irrespective of symptoms, which results in acute LV dilatation and dysfunction, increased LV mass and QT interval prolongation." (PMID 35741162, 2022). "In conclusion, IL-2 therapy is ubiquitously associated with acute cardiopulmonary inflammation, irrespective of symptoms, which leads to acute LV dilatation and dysfunction, increased LV mass and QT interval prolongation." (PMID 35741162, 2022).
disc degeneration (1 paper, 2026). "Longitudinal and tissue-based studies are warranted to validate these findings and explore the therapeutic potential of targeting the miR-186-5p/IL-2 axis in degenerative disc disease." (PMID 41535614, 2026). "The partial recovery of miR-186-5p expression during mid-stage disease, coinciding with peak IL-2 levels, may represent a potential therapeutic window in which restoring miR-186-5p could mitigate inflammation and slow disc degeneration." (PMID 41535614, 2026). "This study offers new proof that patients with lumbar degenerative disc disease have significantly lower levels of HSA-miR-186-5p and higher levels of IL-2." (PMID 41535614, 2026).
DRESS syndrome (1 paper, 2024). "Activated T lymphocytes produced large amounts of tumor necrosis factor-α, interleukin-2, and interferon-γ and considered key mediators of the cytokine release that induces the symptoms found in DRESS syndrome patients." (PMID 39280124, 2024).
echinococcosis (1 paper, 2021). A parasitic infection caused by tapeworm larvae of Echinococcus. "Anti-echinococcosis-related cytokines (IL-2, IL-4, IL-10) were significantly increased." (PMID 34488852, 2021).
fallopian tube carcinoma (1 paper, 2024). A carcinoma that arises from epithelial cells of the fallopian tube. "A clinical trial is currently ongoing in the United States (NCT02498912) utilizing genetically modified T cells secreting IL-2 and targeting the MUC16ecto antigen in patients with recurrent high-grade serous ovarian, primary peritoneal, or fallopian tube carcinoma-expressing MUC16ecto." (PMID 38667465, 2024).
female infertility (1 paper, 2025). Diminished or absent ability of a female to achieve conception. "Of the potential CIPs, IL2 and IL1A had the highest combined score (0.997) in male infertility, and OSM and LIFR had the highest combined score (0.999) in female infertility." (PMID 40070583, 2025).
Flavivirus Infections (1 paper, 2015). Infections with viruses of the genus FLAVIVIRUS, family FLAVIVIRIDAE. "Human CD4+ T cell responses to flavivirus infection display a Th1 cytokine pattern, characterized by expression of interferon gamma (IFN-γ), interleukin-2 (IL-2) and tumor necrosis factor alpha (TNF-α)." (PMID 26465323, 2015).
Focal cortical dysplasia (1 paper, 2024). A type of malformation of cortical development that primarily affects areas of neocortex. "IL‐2 signaling pathway was activated in patients with focal cortical dysplasia (FCD), a cause of intractable epilepsy, and JAK1/3‐STAT5 was the downstream of IL‐2‐dependent signaling pathways contributing to the pathogenesis of FCD." (PMID 38357846, 2024).
folate deficiency (1 paper, 2023). A nutritional condition produced by a deficiency of FOLIC ACID in the diet. "Our study demonstrated that T-cell cytokines, such as IL-2, IFN-γ, and IL-17A/F were significantly increased by the HFF diet, but not folate deficiency." (PMID 37630806, 2023).
gallbladder cancer (1 paper, 2023). "Preclinical studies have revealed that genomic ERBB2/ERBB3 mutations promote PD-L1–mediated immune escape in gallbladder cancer through inhibiting the ability of tumor-reactive T cells and attenuating the release of Interferon (IFN-γ) and Interleukin-2 (IL-2)." (PMID 37681031, 2023).
gastric cardia carcinoma (1 paper, 2022). A carcinoma that arises from epithelial cells of the cardia of stomach. "IL2 G-330T with GT/TT genotypes had a significantly reduced risk of gastric cardia cancer, compared with the GG genotype." (PMID 35884907, 2022). "The study indicates that IL2 G-330T and IL4 T-168C promoter polymorphisms may contribute to the development of gastric cardia cancer in Chinese populations." (PMID 35884907, 2022).
gastrointestinal stromal tumor (1 paper, 2015). "Tregs have been demonstrated to inhibit NK cells from gastrointestinal stromal tumors (GIST) by competing for IL-2 availability and secrete IL-4, indoleamine-2,3-dioxygenase (IDO)." (PMID 25972872, 2015).
glomerulosclerosis (1 paper, 2014). A hardening of the kidney glomerulus caused by scarring of the blood vessels. "Once again, there is a dichotomy between proteinuria and major renal modifications that implies IL-2 effect on proteinuria is ancillary to the mechanism of glomerulosclerosis and of limited importance." (PMID 25343479, 2014). "While, this could explain the acute effect on proteinuria of IL-2 several and crucial aspects related to glomerulosclerosis remain unexplained." (PMID 25343479, 2014). "In all mice (wild type and p2rx7−/−) and irrespective of treatment (IL-2, IL-2/anti-IL-2), LPS was associated with progressive signs of renal pathologic involvement resulting in glomerulosclerosis." (PMID 25343479, 2014). "Renal lesions of glomerulosclerosis were not modified by IL-2 and IL-2/anti-IL-2 implying that other factors influence renal homeostasis following LPS." (PMID 25343479, 2014). "On the other hand, looking at renal histology it is clear that all parameters evaluated (i.e. mesangial hypercellularity and matrix expansion) were not modified by IL-2 and the same amount of glomerulosclerosis after 7 days from LPS was notable in all mice in spite of different treatments." (PMID 25343479, 2014).
glucocorticoid resistance (1 paper, 2019). "Irrespective of glucocorticoid resistance levels, patient levels of CRP (d = 0.23; 95% CI, −0.01 to 0.46), IFN-γ (d = 0.22; 95% CI, −0.02 to 0.47), IL-1β (d = 0.18; 95% CI, −0.24 to 0.61), and IL-2 (d = −0.12; 95% CI, −1.04 to 0.80) were all not significantly different from control." (PMID 31316402, 2019).
Griscelli syndrome (1 paper, 2024). Griscelli syndrome (GS) is characterized by silvery gray sheen of the hair and hypopigmentation of the skin which can be associated to neurological impairment (type 1), immunodeficiency (type 2) or be isolated (type 3). "Some samples from patients with primary HLH (e.g. RAB27A deficiency, also known as Griscelli syndrome) gave normal degranulation results after IL-2 prestimulation." (PMID 38989281, 2024).
gynecologic cancer (1 paper, 2024). "We also describe the results of a prospective pilot study of the modified TIL therapy regimen, which demonstrated the safety and feasibility of the approach using low-dose cyclophosphamide lymphodepletion without intravenous IL-2 administration in advanced gynecologic cancer patients." (PMID 38769543, 2024). "Our modified TIL therapy regimen demonstrated manageable safety, and TILs could survive and proliferate without IL-2 intravenous administration, showing potent efficacy in patients with advanced gynecologic cancer." (PMID 38769543, 2024).
H syndrome (1 paper, 2021). A systemic inherited histiocytosis, with characteristic cutaneous findings accompanying systemic manifestations. "Interestingly, we found that IL-2 levels were increased in the serum of both H syndrome patients with higher proportions of M2 in HS1." (PMID 33284430, 2021).
hantavirus infection (1 paper, 2011). "The early phase of acute hantavirus infection (average 6 days after onset of symptoms) was characterized by significant elevation of cytokine expression of IL-2, IL-6, IL-8, TGF-β1 and TNF-α versus healthy controls." (PMID 22085404, 2011). "To further analyze the relation of pro- and anti-inflammatory cytokines during the course of disease in acute hantavirus infection, we compared expression of IL-2, IL-5, IL-6." (PMID 22085404, 2011). "Acute hantavirus infection was characterized by significantly elevated levels of IL-2, IL-6, IL-8, TGF-β1 and TNF-α in both early and late phase compared to healthy controls." (PMID 22085404, 2011). "Cytokine expression of IL-2, IL-5, IL-6, IL-8, IL-10, IFN-γ, TNF-α and TGF-β1 was analysed by ELISA during the early and late phase of acute hantavirus infection (average 6 and 12 days after onset of symptoms, respectively)." (PMID 22085404, 2011). "Significantly elevated serum levels of IL-2, IL-6, IL-8, TGF-β1 and TNF-α were also observed when the late phase of acute disease was compared with healthy controls, demonstrating a profound and prolonged pro-inflammatory response to hantavirus infection." (PMID 22085404, 2011).
hearing loss (1 paper, 2024). "These cytokines, which act through different pathways (IL-2 in TH1 and IL-5 in TH-2), are associated with hearing loss in a few articles." (PMID 39015324, 2024).
heart transplant (1 paper, 2019). "Researchers have found that IL-2 is increased in heart transplant patients and is specifically involved in cardiac rejection." (PMID 30696462, 2019).
Hydrocephalus (1 paper, 2023). Hydrocephalus is an active distension of the ventricular system of the brain resulting from inadequate passage of CSF from its point of production within the cerebral ventricles to its point of absorption into the systemic circulation. "Both DCX and GPC2 associated with hydrocephalus, NSE, IL-1β, IL-2, IL-8, IL-13." (PMID 36800341, 2023). "Significant, positive associations were found for both CSF-DCX and CSF-GPC2 respectively, with hydrocephalus, NSE, IL-2, IL-8, IL-13, and IL-1β." (PMID 36800341, 2023).
hyperandrogenism (1 paper, 2022). Excessive secretion of androgens from the adrenal glands or gonads. "And there is a randomized controlled trial using BNZ-1, a selective and simultaneous inhibitor of cytokines IL-2, IL-9, and IL-15, for the treatment of hyperandrogen-induced hair loss.It shows that factors that inhibit IL-15 such as BNZ-1 have a role in the treatment of PCOS hyperandrogenism." (PMID 35250857, 2022).
Hypercalcemia (1 paper, 2021). An abnormally increased calcium concentration in the blood. "Stimulated by IFN-γ, tumour necrosis factor-α (TNF-α, IL1 and IL2), macrophages from sarcoid granulomas, can spontaneously release 1,25-dihydroxy vitamin D, further boosting calcium resorption from the gastrointestinal tract and bone, and causing hypercalcemia and hypercalciuria." (PMID 34947932, 2021).
hyperplasia (1 paper, 2022). An abnormal increase in the number of cells in an organ or a tissue with consequent enlargement. "Hyperplasia also occurs on the stimulation of T-lymphocytes that produce several cytokines, such as IFN-γ, IL-2, IL-5, and IL-10, subsequently leading to cell proliferation." (PMID 36614420, 2022).
Hypocholesterolemia (1 paper, 2024). An decreased concentration of cholesterol in the blood. "Interleukin-2, however, can induce hypocholesterolemia by inhibiting the activity of lecithin-cholesteryl acyltransferase (LCAT)." (PMID 38673837, 2024).
hypophysitis (1 paper, 2016). Inflammation of the pituitary gland. "Hypophysitis has also been reported very rarely after treatment with interleukin 2 and interferon." (PMID 28702249, 2016).
Idiopathic intracranial hypertension (1 paper, 2025). "Further, Idiopathic intracranial hypertension (IIH) patients were used as controls in this study despite evidence that this disease is not immunologically inert; IL-2 and IL-17 were found in CSF of IIH patients at higher levels." (PMID 40666507, 2025).
internalizing disorder (1 paper, 2022). A type of mental or behavioral disorder, typically in children and young adults, with symptoms including depression, anxiety and withdrawal. "In pediatric studies, the relationship between IL-2 and internalizing disorders remains unclear." (PMID 35880170, 2022).
interstitial cystitis (1 paper, 2015). A rare chronic debilitating urogenital disease characterized by urinary frequency, urgency, and pelvic pain. "Interstitial cystitis/painful bladder syndrome (IC/PBS) is characterized by increased bladder pain and urinary frequency and associated with increased IL-2, IL-6, IL-8, TNFα expression, and lowered levels of IL-4." (PMID 25962909, 2015).
Interstitial pneumonitis (1 paper, 2014). "However, the interstitial pneumonitis was hardly observed in pMVAX1©-IL-2+pMVAX1©-GP35 and attenuated PRRS vaccine groups, which was significantly milder than that in pVAX1©-IL-2+pMVAX1©-GP35 and pMVAX1©-GP35 groups." (PMID 24603502, 2014).
intestinal obstruction (1 paper, 2017). Blockage of the normal flow of the intestinal contents within the bowel. "Intestinal obstruction led to significant changes in IL-2 and TNF-α compared with the normal control group." (PMID 28953987, 2017). "IL-2 was increased after relieving the intestinal obstruction, while TNF-α was decreased." (PMID 28953987, 2017).
invasive breast carcinoma (1 paper, 2020). A carcinoma that infiltrates the breast parenchyma. "T-cell infiltration in invasive breast cancer has been reported that secrete several inflammatory cytokines, for example interferon-γ (IFNγ), transforming growth factor beta (TGF-β), tumor necrosis factor alpha (TNFα) and interleukin-2 (IL-2)." (PMID 32533334, 2020).
joint disease (1 paper, 2016). "Here, IL-2 Ab Cx was explored as a therapeutic agent to reduce joint inflammation induced by chikungunya virus, an alphavirus causing debilitating joint disease globally." (PMID 27886209, 2016).
kidney tumors (1 paper, 2010). "Coadministration of IL-2 led to enhanced T cell activity as demonstrated by an increased frequency of IFN-gamma-producing T cells in tumor-draining lymph nodes, which may have contributed to the observed improvement of therapy against kidney tumors." (PMID 20426873, 2010).
latent syphilis (1 paper, 2017). A stage of syphilis characterized by the serologic evidence of infection by Treponema pallidum without evidence of accompanying signs or symptoms related to the disease. "They noted a stepwise increase in IL-10 production from primary syphilis to secondary and latent syphilis that correlated inversely with the ability to produce IL-2 (a Th1 cytokine)." (PMID 28143443, 2017).
lumbar degenerative disc disease (1 paper, 2026). "However, the particular interaction between HSA-miR-186-5p and IL-2 in lumbar disc degeneration has not been studied." (PMID 41535614, 2026).
lumbar disc herniation (1 paper, 2024). "In addition, a previous study aimed at understanding the mechanism of EA in the treatment of patients with lumbar disc herniation, which is also a neuro edema disease, and found that EA can effectively reduce the levels of IL-2, TNF-α, and IL-6 contents." (PMID 38689877, 2024).
male infertility (1 paper, 2025). The inability of the male to effect fertilization of an ovum after a specified period of unprotected intercourse. "IL-2 levels in seminal plasma are found to be related to sperm count, motility, and morphology, and may be a potential marker in male infertility." (PMID 40070583, 2025). "Additionally, cytokines, such as IL2 and IL1A had the highest combined score in the PPI network associated with male infertility." (PMID 40070583, 2025).
manic episode (1 paper, 2022). "In patients experiencing a manic episode, pro‐inflammatory cytokines (e.g., TNF‐α, IL‐1, IL‐6), soluble receptors of IL‐2, soluble TNF‐α receptor type 1 (sIL‐2R and sTNFR1, respectively), and C reactive protein (CRP) are generally increased when compared to a control population." (PMID 34590391, 2022).
mast cell tumors (1 paper, 2024). "In addition, intratumoral IL-2 injection has been shown to be safe and to exert clear antitumor effects in dogs with mast cell tumors." (PMID 39728976, 2024).